DPP6 (dipeptidyl peptidase like 6)
Diseases named in the same sentence as DPP6 in open-access papers (continued):
Sharing a sentence is not in itself a finding about the gene and the disease.
neuroblastoma (4 papers, 2017 to 2025). Neuroblastoma (NB) is the most common solid, extracranial childhood tumor. "Another study showed that mutations in the DPP6 gene are more prevalent in the plasma exosomes of patients with neuroblastoma, but its precise role in this disease remains unclear." (PMID 40109277, 2025). "Radioactivity signals from the 99mTc-anti-DPP6 nanobody also showed notably high tumor-to-blood (2.9 ± 0.2 and 2.5 ± 0.4 in mice with neuroblastoma and mice with EndoC-ßH1, respectively) and tumor-to-muscle ratios (9.9 ± 3.2 and 9.9 ± 2.2, respectively)." (PMID 33925941, 2021). "The lead nanobody, 4hD29, was radiolabelled and in vivo SPECT/CT imaging and biodistribution studies were performed in immunodeficient mice transplanted with DPP6-expressing Kelly neuroblastoma cells or insulin-producing human EndoC-βH1 cells." (PMID 29123178, 2017). "An anti-DPP6 nanobody was developed, radiolabeled with 99mTc, and used for SPECT/CT imaging of immunodeficient mice transplanted intramuscularly with DPP6-expressing neuroblastoma cells or insulin-producing human EndoC-ßH1 cells." (PMID 33925941, 2021). "The 99mTc-anti-DPP6 nanobody displayed a two times higher uptake in the neuroblastoma tumor (1.2 ± 0.10% IA/g) than in negative control mice (0.5 ± 0.1% IA/g)." (PMID 33925941, 2021).
acute myeloid leukemia (3 papers, 2013 to 2020). Acute myeloid leukemia (AML) is a group of neoplasms arising from precursor cells committed to the myeloid cell-line differentiation. "In contrast, hypermethylation and reduced expression of Dpp6 is observed in melanoma and acute myeloid leukemia (AML) patients." (PMID 23409053, 2013).
clear cell renal cell carcinoma (3 papers, 2021 to 2022). "DPP6 served as a tumor-specific hypermethylated gene and was significantly related to the prognosis of clear cell renal cell carcinoma patients." (PMID 34359286, 2021). "However, in surgically treated clear cell renal cell carcinoma (ccRCC) patients, the promoter methylation of DPP6 genes is related to an aggressive phenotype and early progression of distant metastasis." (PMID 36531033, 2022). "A previous study involving analysis of TCGA data reported that DPP6 induces tumorigenesis in GBM and correlates with prognosis in clear cell renal cell carcinoma." (PMID 35887658, 2022).
diabetes (3 papers, 2017 to 2021). "Recently, dipeptidyl-Peptidase 6 (DPP6) was identified as a target to evaluate the endocrine cell mass in vivo, for the visualization of the progressive β-cell loss in diabetes or after islet transplantation." (PMID 33353213, 2020). "A systems biological approach and RNA sequencing of pancreatic islets helped identify dipeptidyl-peptidase 6 (DPP6) as a highly specific pancreatic biomarker for diabetes and insulinomas." (PMID 33925941, 2021). "In this context, it is important to identify targets that are not affected by inflammatory or metabolic stress, which is the case of DPP6, allowing the estimation of beta cell mass unaffected by the stressful conditions to which islet cells are exposed in diabetes or following transplantation." (PMID 29123178, 2017).
Gilles de la Tourette syndrome (3 papers, 2019 to 2022). "The mutation of DPP6 has been reported in Gilles de la Tourette syndrome (GTS)." (PMID 36012450, 2022).
memory impairment (3 papers, 2017 to 2021). "This proved that DPP6 was associated with some neurological diseases, including cognitive diseases and memory impairment." (PMID 34639784, 2021).
microcephaly (3 papers, 2018 to 2022). A congenital or acquired developmental disorder in which the circumference of the head is smaller than normal for the person's age and sex. "A missense mutation in the DPP6 gene was identified in a family segregating microcephaly and autosomal dominant ID." (PMID 36012450, 2022). "Studies indicate that the DPP6 gene is associated with microcephaly and mental retardation." (PMID 29651237, 2018). "SRO023 contains DPP6, which is associated with hereditary ventricular fibrillation, as well as autosomal dominant (AD) microcephaly and neurodevelopmental delay which was replicated on knockdown of DPP6 in mice." (PMID 35457073, 2022). "Recently, missense variations of DPP6 have been identified in human patients with microencephaly." (PMID 36012450, 2022).
pancreatic cancer (3 papers, 2010 to 2022). "Several SNPs located in the first intron of DPP6 indicated suggestive associations with an increased risk of pancreatic cancer in this study." (PMID 20686608, 2010). "A recent study on core signaling pathways in human pancreatic cancers found three somatic mutations in DPP6 among 24 pancreatic cancer samples examined by detailed sequence analyses." (PMID 20686608, 2010). "Hence, our study strengthens the risk of DPP6 in pancreatic cancer and warrants further screening on this gene to confirm its association with pancreatic cancer." (PMID 20686608, 2010).
pancreatic ductal adenocarcinoma (3 papers, 2020 to 2022). An infiltrating adenocarcinoma that arises from the epithelial cells of the pancreas. "The methylation of CG sites in the DPP6 promoter was reported to be in greater numbers in tumor samples compared to normal samples from pancreatic ductal carcinoma; thus, the hypermethylation of DPP6 promoter is associated with poor overall survival." (PMID 35565241, 2022). "Similarly, in pancreatic ductal adenocarcinoma tissues, the promoter methylation of DPP6 genes is significantly higher than that in normal tissues." (PMID 36531033, 2022).
schizophrenia (3 papers, 2022 to 2025). A major psychotic disorder characterized by abnormalities in the perception or expression of reality. "DPP6 also has been reported as a putative candidate gene for schizophrenia with very rare CNVs." (PMID 36012450, 2022). "By using a genome-wide SNP array in schizophrenia patients with or without treatment-resistant TD, they showed that DPP6 is a promising association gene with the SNP located in intron-1 and associated with decreased DPP6 expression in the human postmortem prefrontal cortex." (PMID 36012450, 2022).
ventricular fibrillation (3 papers, 2015 to 2025). A disorder characterized by an electrocardiographic finding of a rapid grossly irregular ventricular rhythm with marked variability in QRS cycle length, morphology, and amplitude. "As described in the section on the risk of ventricular fibrillation associated with DPP6 mutations, the effects of DPP6 overexpression are more pronounced in PF than in VM." (PMID 40109277, 2025). "This gene shows signals of recent adaptive protein evolution and variants in the regulatory region of DPP6 are associated with ventricular fibrillation." (PMID 26077037, 2015).
Anxiety (2 papers, 2017 to 2018). Intense feelings of nervousness, tension, or panic often arise in response to interpersonal stresses. "We also tested anxiety level in DPP6-KO mice by the elevated plus-maze." (PMID 29651237, 2018). "Interestingly, Dpp6 (dipeptidyl peptidase-like 6), with expression parallel to the increased anxiety of PrePubOVX WMI females is also a candidate gene for ALS." (PMID 29403433, 2017).
Azoospermia (2 papers, 2019 to 2022). Absence of any measurable level of sperm,whereby spermatozoa cannot be observed even after centrifugation of the semen pellet. "It was demonstrated that two disrupted genes, DPP6 and CACNA2D1, were at breakpoint sites of the chromosomes, suggesting they may be associated with azoospermia." (PMID 31231514, 2019).
epilepsy (2 papers, 2018 to 2019). A brain disorder characterized by episodes of abnormally increased neuronal discharge resulting in transient episodes of sensory or motor neurological dysfunction, or psychic dysfunction. "Both loci include multiple potential candidate genes, including IGF1R, CNTNAP2, and DPP6, all are well‐studied genes that are strongly associated with developmental and speech delays, congenital heart disease, epilepsy, diaphragmatic hernia, renal anomalies, and ID." (PMID 31475484, 2019).
Hypertension (2 papers, 2017 to 2021). The presence of chronic increased pressure in the systemic arterial system. "However, we are unable to corroborate a direct effect for NUP210, GAL2 and DPP6 on blood pressure and hypertension, but we suggest that these genes could be indirectly related to blood pressure and hypertension." (PMID 28924246, 2017).
insulinomas (2 papers, 2017 to 2021). "We presently identified DPP6 as a new biomarker of the endocrine pancreas, expressed preferentially in human beta and alpha cells and also in insulinomas." (PMID 29123178, 2017). "Interestingly, DPP6 expression was also clearly present in the insulin positive cells from two separate human insulin producing tumors (insulinomas)." (PMID 29123178, 2017).
Ataxia (1 paper, 2021). Ataxia refers to impaired coordination of voluntary muscle movement. "This is in contrast to neuronal antibodies that have already been shown to be directly involved in the pathogenesis of ataxia (e.g. dipeptidyl-peptidase-like-6 [DPPX], metabotropic glutamate receptor 1 [mGluR1], glutamic acid decarboxylase [GAD]-65)." (PMID 34489848, 2021).
atherosclerosis (1 paper, 2022). A disease characterized by the build-up of fatty material and calcium deposition in the arterial wall resulting in partial or complete occlusion of the arterial lumen. "Our study suggests that rare variation in genes including AMPD3, MICAL2, DPP6, and DENND2B may play a role in subclinical atherosclerosis, thereby making them promising novel candidates for the development of anti-atherosclerotic therapies." (PMID 35020748, 2022).
brain cancer (1 paper, 2022). A primary or metastatic malignant neoplasm affecting the brain. "For the PPI network, primarily signals in the malignant brain neoplasm associated with DPP6, RBFOX1, LMF1, and EDARADD to present regulation of alternative splicing of RNA by APP6 and RBFOX1, maturation of specific proteins in ER by LMF1, and activation of NF-κB through EDARADD." (PMID 35887658, 2022). "DPP6 enzyme activity is particularly found in humorous brain tumors, which suggests that DPP6 expression correlates with the formation of brain neoplasms." (PMID 35887658, 2022).
Brugada syndrome (1 paper, 2023). A genetically heterogeneous condition characterized by complete or incomplete right bundle branch block accompanied by ST elevation in leads V1-V3. "A similar observation in DPP6 is that administration of ajmaline (e.g. to rule out Brugada syndrome in IVF patients who were not yet identified as DPP6 carrier) may aggravate the phenotype and can result in short-coupled IVF (without signs of Brugada syndrome)." (PMID 37498467, 2023).
cervical cancer (1 paper, 2024). A primary or metastatic malignant neoplasm involving the cervix. "Detecting the methylation of the DPP6, RALYL, and GSX1 genes was also used for the early diagnosis of cervical cancer in women in Stockholm, Sweden." (PMID 39766341, 2024).
cognitive decline (1 paper, 2025). "A recent study has revealed that DPP6 is one of the factors contributing to cognitive decline in Parkinson’s disease." (PMID 40109277, 2025).
COVID-19 (1 paper, 2022). A disease caused by infection with severe acute respiratory syndrome coronavirus 2. "Particularly, this study reports upregulated ADA, BTC, DPP6, EDIL3, LIF, ENTPD2, Flt3L, and LRP1 in severe COVID-19 patients for the first time." (PMID 36428847, 2022). "Furthermore, this study reports markers including ADA, BTC, DPP6, EDIL3, LIF, ENTPD2, Flt3L, and LRP1 to be upregulated in severe COVID-19 patients; hence, they are proposed as novel biomarkers for severe cases of COVID-19." (PMID 36428847, 2022).
Depression (1 paper, 2026). "Critically, aged DPP6-KO mice exhibited decreased REM latency, a biomarker of depression, which we confirmed by behavioral assays." (PMID 41977406, 2026).
dissociative disorder (1 paper, 2022). A category of psychiatric disorders which are characterized by a disruption in the usually integrated functions of consciousness, memory, identity, and/or perception of the environment. "Both ADYC8 and DPP6 have also been linked to brain development in childhood, which may be of relevance to dissociative disorders associated with trauma-related alterations in brain development." (PMID 35627228, 2022).
encephalitis (1 paper, 2017). An acute inflammatory process affecting the brain parenchyma. "Within the past decade, the auxiliary subunit DPP6, also called DPPX, has been associated with encephalitis." (PMID 28484374, 2017).
endometriosis (1 paper, 2014). The growth of functional endometrial tissue in anatomic sites outside the uterine body. "Two SNPs within the 22 CNVRs show significant genotypic association with endometriosis after adjusting for multiple testing; rs758316 in DPP6 on 7q36.2 (P = 0.0045) and rs4837864 in ASTN2 on 9q33.1 (P = 0.0002)." (PMID 25083881, 2014).
esophagus adenocarcinoma (1 paper, 2020). "Similarly, the promoter of DPP6 was also found to be hypermethylated in a TCGA esophagus adenocarcinoma cohort." (PMID 32701143, 2020).
gastric cancer (1 paper, 2026). A primary or metastatic malignant neoplasm involving the stomach. "Transcriptomic analysis demonstrated significant downregulation of DPP6 and DLG2, while KDM4D, USP34, and VDR were significantly upregulated in gastric cancer tissues compared with normal controls." (PMID 42195053, 2026).
insomnia (1 paper, 2026). A sleep disorder characterized by difficulty in falling asleep and/or remaining asleep. "The progressive nature of sleep dysfunction in DPP6-KO mice, from REM abnormalities to insomnia, parallels human disease progression and positions DPP6 as a potential therapeutic target for sleep-related symptoms in neurodegenerative disorders." (PMID 41977406, 2026).
Kleefstra syndrome 2 (1 paper, 2023). "A 7q36.1q36.2 deletion containing several pathogenic genes, including DPP6, KMT2C, ASB10, PRKAG2, KCNH2, among which KMT2C is a causative gene for Kleefstra syndrome 2 (MIM#617768)." (PMID 37892645, 2023).
lung carcinoma (1 paper, 2021).
multiple sclerosis (1 paper, 2025). A progressive autoimmune disorder affecting the central nervous system resulting in demyelination. "A study on multiple sclerosis in the Nordic population showed that DPP6 levels were elevated in PBMCs of PrMS patients, although DPP6 is known to be mainly expressed in the brain and spinal cord, and DPP6 downregulation was observed in spinal motor neurons induced by SBMA iPSC differentiation." (PMID 40109277, 2025).
muscle atrophy (1 paper, 2022). The loss of muscle tissue due to inactivity or disease. "This suggests that DPP6 acts as a susceptibility gene for muscle atrophy symptoms in humans." (PMID 35368668, 2022).
neurodevelopmental disabilities (1 paper, 2018). "Low birth weight is associated with neurodevelopmental disabilities in humans, and DPP6 gene loss is related to developmental disorders." (PMID 29651237, 2018).
renal cell carcinoma (1 paper, 2020). "In renal cell carcinoma, the promoter hypermethylation of DPP6 frequently occurred in tumor cells and was associated with poor survival serving as an independent predictor for distant metastasis." (PMID 32701143, 2020).
thyroid cancer (1 paper, 2023). "Regarding PTGFR and DPP6, to our knowledge, both genes fail to be associated with thyroid cancer to date." (PMID 37372430, 2023). "The results revealed that all the genes are highly relevant in the context of thyroid cancer and, more particularly interesting, PTGFR and DPP6 have not yet been associated with the disease up to date, thus making them worthy of further investigation as to their relationship to PTC." (PMID 37372430, 2023).
tic disorder (1 paper, 2022). Disorders characterized by recurrent TICS that may interfere with speech and other activities. "DPP6, which encodes a potassium channel subunit related to the excitability of neuronal dendrites and synaptic integration, has been associated with tic disorder." (PMID 35627228, 2022).
type 1 diabetes (1 paper, 2017). "Analysis of pancreata obtained from patients with long-term type 1 diabetes (n = 3) showed nearly complete loss of insulin positive cells, while some DPP6 and glucagon positive cells remained." (PMID 29123178, 2017).